EPHA2 (EPH receptor A2)
Diseases named in the same sentence as EPHA2 in open-access papers (continued):
Sharing a sentence is not in itself a finding about the gene and the disease.
breast cancer (continued). "Recently, we have demonstrated the role of EphA2 (Ephrin type A receptor 2) in breast cancer aggressiveness and TrkA TKI resistance." (PMID 37046604, 2023). "Upregulation of EphA2 reduced dependence on the oestrogen receptor function, hence diminishing tamoxifen’s capacity to suppress breast cancer cell proliferation and carcinogenesis." (PMID 36830852, 2023). "Increasing evidence has shown that EphA2 is highly expressed in a variety of human cancers, such as breast cancer, prostate cancer, lung cancer, colon cancer, and skin cancer." (PMID 37063424, 2023). "We further found that Shc3 acts as a link mediating the binding between EphA2 and ErbB2 in breast cancer cells, resulting in increased activation of MAP kinase and AKT signaling pathways." (PMID 36880347, 2023). "This study presents LINC02086/miR-6757-5p/EPHA2 axis as promising therapeutic targets for breast cancer intervention." (PMID 38008720, 2023). "Previous studies demonstrate that ephrin type-A receptor 2 (EPHA2) is highly expressed in breast cancer and acts as a key oncogenic tyrosine kinase in tumorigenesis." (PMID 38008720, 2023). "LINC02086 increases cell viability and decreases apoptotic cells in breast cancer by sponging miR-6757-5p to upregulate EPHA2." (PMID 38008720, 2023). "Functional assays on MDA-MB-231 have shown that Sortilin inhibition alters cell proliferation, survival and adhesion in vitro and we have shown that a ternary complex between Sortilin/TrkA/EphA2 is involved in breast cancer cells." (PMID 37576898, 2023). "A breast cancer study demonstrated that EphA2 in circulating exosomes indicates poor prognosis and metastasis." (PMID 37907962, 2023). "EphA2 is also overexpressed and associated with poor prognosis in breast cancer, where it amplifies oncogenic signalling of the RTK erbB2 (HER2), and the loss of EphA2 in the mammary epithelium of mice slowed down tumour development and metastasis." (PMID 36830852, 2023). "Analysis by the breast cancer database (bc-GenExMiner v4.5) showed a positive correlation between EphA2 and KLF5 in basal-like patients (R=0.30, n=783) and all breast cancer patients (R=0.36, n=4421)." (PMID 37063424, 2023). "IHC staining of BLBC clinical specimens from breast cancer patients with NCT showed that high expression of EphA2 pS897 was more frequent in chemoresistant samples than in chemosensitive samples." (PMID 37063424, 2023). "RNF5 depletion resulted in increased adhesion in four lines of HER2-negative breast cancer cells, while EphA2 depletion decreased adhesion and abolished the increase in adhesion in cells with RNF5 depletion." (PMID 37816703, 2023). "Altogether, these results indicate that RNF5 promotes the tumorigenesis of HER2-negative breast cancer cells by decreasing the EphA2 level." (PMID 37816703, 2023). "Ephrin type A receptor 2 (EphA2) is expressed in paediatric sarcomas and paediatric high-grade gliomas (HGGs), glioblastoma multiforme, breast cancer, NSCLC and oesophageal cancer." (PMID 36829563, 2023). "We investigated the effect of the RNF5-EphA2 level in breast cancers, and then, the survival of breast cancer patients was analyzed with RNF5 and EphA2 levels." (PMID 37816703, 2023). "The analysis of RNA-seq levels from TCGA database showed that RNF5 was negatively correlated with EphA2 (coefficients < 0, p < 0.01) in breast cancers." (PMID 37816703, 2023). "Previous studies have found that EPHA2﻿ promotes breast cancer cell proliferation, migration, and invasion." (PMID 38008720, 2023). "In conclusion, our findings demonstrated a critical role of EPHA2-rich exosomes in promoting angiogenesis and metastasis of breast cancer." (PMID 35673569, 2022). "The data showed that the expression of EPHA2 was higher in breast cancer tissues than in paracancer tissues." (PMID 35673569, 2022).
breast cancer (continued). "Taken together, these results suggest that breast cancer cell-derived exosomal EPHA2 promotes angiogenesis by activating the downstream AMPK- HIF1-α pathway through Ephrin A1-EPHA2 forward signaling." (PMID 35673569, 2022). "Next, HM breast cancer cells with stable knockdown of EPHA2 were constructed, and their exosomes were collected to treat endothelial cells." (PMID 35673569, 2022). "Herein, we identified a novel model, in which EPHA2-rich exosomes derived from HM breast cancer cells can promote the angiogenic potency of endothelial cells." (PMID 35673569, 2022). "We recently found that EPHA2 is enriched in drug-resistant breast cancer cells and their exosomes, and the exosomal EPHA2 is required for breast cancer cell metastasis." (PMID 35673569, 2022). "In this study, we demonstrated a high EPHA2 protein expression in half of our TNBC breast cancer tissue samples." (PMID 35204461, 2022). "Together, these results suggest that exosomal EPHA2 can promote the angiogenesis and metastasis of breast cancer cells in vivo." (PMID 35673569, 2022). "In conclusion, these results suggest that exosomal EPHA2 is a critical mediator for HM breast cancer cells to promote angiogenesis." (PMID 35673569, 2022). "Collectively, our results suggest that exosomal EPHA2 derived from HM breast cancer cells promotes breast cancer progression through the AMPK-HIF-1α pathway downstream of Ephrin A1-EPHA2 forward signaling." (PMID 35673569, 2022). "Exosomal EPHA2 transferred from HM breast cancer cells to endothelial cells confers the pro-angiogenic effect by activating AMPK signaling through a ligand Ephrin A1-dependent forward pathway." (PMID 35673569, 2022). "Clinical trials have demonstrated dasatinib has a certain efficacy towards EphA2-correlated breast cancer and non-small cell lung cancer." (PMID 36142306, 2022). "The results showed that the levels of exosomal EPHA2 were significantly higher in plasma from breast cancer patients than those from healthy blood donors." (PMID 35673569, 2022). "In this study, we demonstrated that EPH receptor A2 (EPHA2) is enriched in exosomes derived from breast cancer cells with high metastatic potential (HM) and promotes angiogenesis and metastasis." (PMID 35673569, 2022). "Given that the metastatic ability of resistant cells in our study is stronger than that of sensitive cells, we tested the expression levels of EPHA2 in breast cancer cell lines with different metastatic potential." (PMID 35673569, 2022). "Investigation of the role of the EPH/ephrin system in breast cancer has mainly focused on the receptors EPHA2, EPHB4, and EPHB6." (PMID 35204461, 2022). "Collectively, we demonstrated that HM breast cancer cells enhance their metastatic ability by promoting angiogenesis through exosomal EPHA2." (PMID 35673569, 2022). "Concerning breast cancer human material in general, some recent studies have attempted to link the expression of EPHA2, EPHA4, and EPHA7 with clinicopathologic parameters and/or survival." (PMID 35204461, 2022). "In a later publication using a tyrosine antibody array, several RTKs able to bind to PKM2 were detected, and their ability to phosphorylate PKM2 was confirmed when overexpressed in a breast cancer cell line (Axl, EpHA2, FAK, Tyro3, ErbB2, 29440169)." (PMID 35054968, 2022). "Despite its low expression in normal mammary epithelium, EPHA2 is overexpressed in the majority of breast cancers." (PMID 35204461, 2022). "Investigations from various development groups have provided compelling evidence about the role of EPHA2 in breast cancer." (PMID 35204461, 2022).
breast cancer (continued). "EphA2 is also overexpressed in various cancer cell lines, such as fibrosarcoma, breast cancer, and ovarian cancer, and high EphA2 levels are correlated with increased malignancy and poor clinical prognosis." (PMID 36132127, 2022). "Exosomal EPHA2 can be transferred from HM breast cancer cells to endothelial cells to mediate the upregulation of EPHA2 in endothelial cells." (PMID 35673569, 2022). "Our group has previously shown EphA2 hyperphosphorylation in esophageal cancer based on cell line phosphotyrosine profiling data, whereas EphA2 and EphB4 have been upregulated in breast cancer." (PMID 34298619, 2021). "For instance, inverse expression of ephrin-A1 and EphA2 in human breast cancer cell lines was a frequent finding." (PMID 33572284, 2021). "DR-Exos treated with ALW-II-41-27 still exerted profound migratory promoting ability, which indicated that exosomal EphA2 promoted breast cancer migration through EphA2-Ephrin A1 reverse signaling instead of the kinase-related forward signaling." (PMID 33879771, 2021). "To investigate the efficacy of an EphA2 pharmacologic inhibitor on breast cancer–induced osteolysis, we treated bone tumor–bearing animals with EphA2 small‐molecule inhibitor ALW‐II‐41‐2725, 43 or vehicle control." (PMID 33869989, 2021). "Data from coculture studies suggest that EphA2 induction of osteoclast differentiation by breast cancer cells involves a soluble factor(s) whose expression is regulated by EphA2." (PMID 33869989, 2021). "The level of circulating exosomal EphA2 in the plasma of breast cancer patients was significantly higher than that of healthy donors." (PMID 33879771, 2021). "Endogenous Pparγ1 induced expression of both an EphA2-Amphiregulin and an inflammatory INFγ and Cxcl5 signaling module, that was recapitulated in human breast cancer." (PMID 33946495, 2021). "In slight contrast to the distinct upregulation or downregulation already mentioned in breast cancer (see Section 3), the expression levels of EphA1 and EphA2 were found to differ between the stages of colorectal cancer." (PMID 33430066, 2021). "The best characterised Eph receptors in breast cancer are EphA2 and EphB4, but there are also others that have been found to play a role." (PMID 33430066, 2021). "EphA2, the main EphA receptor to have been extensively studied for its involvement in breast carcinomas, is overexpressed in 40% of breast cancers and is generally correlated with a poor prognosis." (PMID 33430066, 2021). "EphA2 was shown to be upregulated in TNBC whereas estrogens downregulate it in ER+ breast cancer (reviewed in." (PMID 34490074, 2021). "EphA2, which is known to augment ErbB2-induced mammary tumorigenesis, was increased 4-fold in the Pparγ1+/+ ErbB2 mammary tumors." (PMID 33946495, 2021). "We report that these streptavidin-based EphA2 targeting agents induce superior receptor degradation in triple-negative MDA-MB-231 breast cancer cells and BxPC3 pancreatic-cancer cells." (PMID 34204178, 2021). "Transcript levels of EPHA2 were significantly higher in breast cancer bone metastases relative to other metastatic sites including brain, lung, and liver in two independent datasets (p < 0.05)." (PMID 33869989, 2021). "In breast cancer, phosphorylated EPHA2 activated AKT through PI3K to participate in trastuzumab resistance." (PMID 33834064, 2021). "Conversely, a knockdown of EphA2 resulted in a reduction in tumorigenicity in human breast cancer cells." (PMID 33430066, 2021). "In this study, we reported that the exosomes released by drug-resistant breast cancer cells were rich in EphA2 protein." (PMID 33879771, 2021). "The mechanism whereby exosomal EphA2 enhances the aggressive behavior of breast cancer cells needs further investigation." (PMID 33879771, 2021). "In our models of breast cancer, elevated EphA2 expression in tumor cells appears to be required for tumor‐induced osteolytic disease." (PMID 33869989, 2021).
breast cancer (continued). "Collectively, our results suggest that exosomal EphA2 derived from drug-resistant cells promotes breast cancer progression through the ERK pathway downstream of EphA2-Ephrin A1 reverse signaling." (PMID 33879771, 2021). "Collectively, these findings indicated that exosomal EphA2 derived from drug-resistant cells promoted breast cancer progression through ERK signaling." (PMID 33879771, 2021). "Ephrin type-A receptor 2 (EphA2) promotes membrane-anchored membrane type-1 matrix metalloproteinase (MT1-MMP) expression in invasive breast cancer cells." (PMID 36046433, 2021). "It was found that the EphA2 function in breast cancer cells promotes osteoclast activation and the development of osteolytic bone disease." (PMID 33869989, 2021). "Collectively, these results indicated that exosomal EphA2 promoted breast cancer cell migration and invasion by inducing Ephrin A1 reverse signaling." (PMID 33879771, 2021). "Here, we show that the EphA2 function in breast cancer cells promotes osteoclast activation and the development of osteolytic bone disease." (PMID 33869989, 2021). "Although the role of EphA2 in breast cancer and visceral metastasis has been well‐established, it is crucial to perform preclinical studies in clinically relevant models of metastasis at different anatomic sites." (PMID 33869989, 2021). "Herein, exosomes carrying EphA2 or its mutants can promote the invasive potential of sensitive breast cancer cells, whereas exosomes carrying EphA2-ΔL lost the ability to promote cell invasion." (PMID 33879771, 2021). "Recently, EphA2 expression has been reported to be significantly correlated with VM and to contribute to poor prognosis in breast cancer patients." (PMID 32116702, 2020). "Unsurprisingly, ephrin A1–PE38QQR was cytotoxic to glioblastoma, breast cancer, and prostate cancer cells that overexpress EphA2." (PMID 32811512, 2020). "Our results should incentivize further efforts aimed at developing potent and effective EphA2 synthetic agonistic agents for the treatment of EphA2-driven aggressive metastatic tumors including prostate, pancreatic, and breast cancer." (PMID 33023262, 2020). "The recent study revealed that HDAC2 and HDAC4 promote the oncogenicity of breast cancer cells by upregulating EphA2 expression and phosphorylation." (PMID 32376822, 2020). "3F2-3M administration dose-dependently increased EphA2 phosphorylation in the breast cancer cell line, which was similar to that of the parental antibodies 3F2-WT and B233." (PMID 32811512, 2020). "The recent study revealed that upregulation of EphA2 by HDAC2 and HDAC4 plays a crucial role in breast cancer, and HDACs-EphA2 signaling axis is a promising therapeutic target for advanced breast cancer." (PMID 32376822, 2020). "In particular, high EphA2 expression in malignant tumors has been shown to be associated with poor prognosis in NSCLC, hepatocellular carcinoma, and breast cancer." (PMID 33092175, 2020). "Overexpression of EphA2 and EphA4 has been reported in gastric cancer, breast cancer, colon cancer, and prostate cancer (17, –, 24)." (PMID 30782663, 2019). "Both EphA2 and EphA4 are overexpressed in numerous malignancies, including gastric cancer, breast cancer, colon cancer, and prostate cancer (17, –, 24)." (PMID 30782663, 2019). "Cleavage at the Gly391-Leu392 bond promoted EphA2 internalization and single cell breast carcinoma invasion, while cleavage at Ser432-Tyr433 promoted ligand-independent activation of RhoG by EphA2 and epidermoid carcinoma cell migration." (PMID 31137480, 2019). "As a consequence, SP1 recruitment on the EphA2 promotor was diminished leading to decreased levels of EphA2, a protein which strongly correlates with agressiveness in breast cancer." (PMID 29754883, 2018). "Research has shown that overexpression of EphA2 in breast cancer cells promotes resistance to trastuzumab, a human monoclonal anti-HER2 antibody used for breast cancer treatment." (PMID 28624791, 2017).
breast cancer (continued). "EphA2 is over-expressed in breast cancer cells and its over-expression correlates with decreased EfnA1 expression and loss of estrogen receptor expression." (PMID 28883622, 2017). "Increased EphA2 expression in Her2-positive breast cancer patients correlates with decreased disease-free and overall survival." (PMID 28883622, 2017). "EphA2 is cleaved upon stimulation of MDA-MB-231 breast cancer cells with FVIIa, with the truncated EphA2 isoform appearing as band migrating around 95 kDa on SDS-PAGE." (PMID 27246245, 2016). "EPHB1 showed the highest relative mRNA expression in the breast cancer samples and EPHA2 the lowest." (PMID 26870995, 2016). "We observed that TF and EphA2 co-localized in MDA-MB-231 breast cancer cells with high endogenous TF expression, and in U251 glioblastoma cells with forced overexpression of TF." (PMID 27246245, 2016). "Hitherto several groups have studied the connections between the EPH family and breast cancer where EPHA2 and EPHB4 are two of the most investigated EPH receptors with potential clinical relevance." (PMID 26870995, 2016). "EPHA2 was found to be overexpressed in a variety of human cancers, including breast cancer, and overexpression of EPHA2 has been shown to promote cancer cell motility and invasion." (PMID 26356563, 2015). "EphA2 is a receptor tyrosine kinase for Ephrin1 and plays a key role in promoting progression and metastasis of various tumor cells including breast cancer." (PMID 24586375, 2014). "In breast cancer model systems, Ephrin-A1 signaling through the EphA2 receptor on the tumor cell can inhibit tumorigenesis, whereas excess unliganded EphA2 promotes tumorigenesis through enhanced proliferation and migration." (PMID 24890385, 2014). "Breast cancer cell lines known to express the target antigens ErbB2, EphA2, EphB3, and CD44 with high and low levels were stained with the identified phage mAbs and evaluated by fluorescence microscopy." (PMID 25353955, 2014). "This study suggested that cleavage and endocytosis of EphA2 by MT1-MMP expressed on single breast cancer cells is required for cell–cell repulsion." (PMID 24795148, 2014). "We have also previously shown that the level of expression of CAV- 1, CAV-2 and EphA2 protein correlated with sensitivity to dasatinib in breast cancer cell lines." (PMID 25594008, 2014). "Previously, we showed that the extracellular domains of EphA2 and CD44 can be displayed on the yeast cell surface and used to identify mAbs from a phage antibody library pre-selected on breast cancer cells overexpressing EphA2 and CD44." (PMID 25353955, 2014). "In breast cancer, elevated RNA expression of EphA4 had significant prognostic value, as did EphA2, EphA7, and EphB4." (PMID 23738943, 2013). "The commercially available top-scoring compounds were screened for their ability to induce EphA2 activation in MDA-MB-231 breast cancer cells." (PMID 22916121, 2012). "The EphA2 expression level in breast cancer cells has been found inversely related to ER expression." (PMID 22417809, 2012). "Although we did not observe any significant associations with ephrin ligand expression and clinical outcome, co-expression of EphA2 and ephrin-A1 in Stage I breast cancers correlated with recurrence." (PMID 21935409, 2011). "Our profiling data are consistent with previous studies reporting that EphA2 is expressed at low levels in normal breast epithelium and overexpressed in 60–80% of breast cancers." (PMID 21935409, 2011). "For example, analysis of EPHA2 knockout mice revealed that EPHA2 enhances ErbB2-mediated tumorigenesis in MMTV-Neu mammary tumor mouse models." (PMID 20979646, 2010). "EphA2 formed a complex with ErbB2 in both human and murine breast carcinoma cells, leading to enhanced signaling through Ras-MAPK activation and ultimately promoting tumor progression." (PMID 20064265, 2010).